HLA-DQB1 (major histocompatibility complex, class II, DQ beta 1)
Diseases named in the same sentence as HLA-DQB1 in open-access papers (continued):
Sharing a sentence is not in itself a finding about the gene and the disease.
autoimmune disease (21 papers, 2009 to 2025). A disorder resulting from loss of function or tissue destruction of an organ or multiple organs, arising from humoral or cellular immune responses of the individual to their own tissue constituents. "Deleterious mutations in HLA-DQB1 are highly associated with common autoimmune diseases such as celiac disease and multiple sclerosis (MS)." (PMID 39358801, 2024). "Similarly, by promoting the presentation of autoantigens and maintaining chronic inflammation, particular HLA-DQB1 alleles are closely linked to an elevated risk of developing autoimmune disorders, such as Sjögren’s Syndrome." (PMID 40321894, 2025). "The HLA-DQB1 belongs to class II, is mainly involved in the actions of the human immune system and plays a fundamental role in donor-recipient matching in transplantation and can be associated with most autoimmune diseases." (PMID 37201029, 2023). "On the other hand, HLA-DQB1 is more likely associated with autoimmune diseases." (PMID 35486660, 2022). "Typically, specific genotypes of HLA-DQB1 were studied with respect to the development of autoimmune diseases." (PMID 39796277, 2025). "HLA-DQB1 was eliminated from further downstream analysis because it is a known prerequisite genetic factor involved in developing autoimmune diseases like celiac disease and rheumatoid arthritis." (PMID 35692981, 2022). "Based on the diverse systems biology and functional annotations of the 7 query genes, ITGAV, FN1, and HLA-DQB1 were prominent in autoimmune diseases." (PMID 35692981, 2022). "An intergenic single-nucleotide polymorphism (SNP), rs9275596, located between the HLA-DQB1 and HLA-DQA2 genes, is in significant association with various autoimmune diseases according to genome-wide association studies (GWASs)." (PMID 32244438, 2020). "It has been reported that specific allelic combinations of HLA-DQA1, HLA-DQB1, and HLA-DRB1 genes influence autoimmune disease predisposition, and, furthermore, their expression levels may also correlate with causes of the disease." (PMID 32547543, 2020). "Besides, HLA-DQB1 plays an important role in ageing-related chronic diseases, including age-related macular degeneration, ischemic stroke, neurodegenerative diseases, chronic back pain, and osteoporosis, as well as autoimmune diseases." (PMID 37744379, 2023). "In contrast, our findings indicate that HLA-B*08:01, HLA-DQB1*02:01, and HLA-DRB1*03:01 have modest protective effects in depression, indicating that these alleles do not harbor shared risk for autoimmune disease and depression." (PMID 31570195, 2020). "Further analyses using imputed HLA allele frequencies indicated that especially HLA genes HLA-A, HLA-DRB1, HLA-DRB4, HLA-DQA1, and HLA-DQB1 may play a role in endodontic infections independent of autoimmune diseases." (PMID 40701953, 2025).
celiac disease (16 papers, 2012 to 2025). An autoimmune genetic disorder with an unknown pattern of inheritance that primarily affects the digestive tract. "However, a significant genetic risk factor for celiac disease is HLA-DQB1, which promotes the presentation of gluten-derived antigens and initiates T-cell-mediated inflammation." (PMID 40321894, 2025). "Different types of HLA complexes such as HLA-DQ2.5 (HLA-DQA1*05/HLA-DQB1*02), HLA-DQ8 (HLA-DQA1*03/HLA-DQB1*03:02), and HLADQ2.2 (HLA-DQA1*02:01/HLA-DQB1*02) are associated with coeliac disease pathogenesis and have been reported in more than 90% of coeliac disease patients." (PMID 32651763, 2020). "a common inflammatory response pathway is highlighted by the correlation between the function of HLA-DQB1 in antigen presentation in celiac disease and TNFAIP3 in the NF-KB pathway in NHL." (PMID 40321894, 2025). "Celiac disease is a common multifactorial disorder in which specific HLA-DQA1 and HLA-DQB1 alleles represent the major genetic predisposition." (PMID 23050549, 2012). "So far, only HLA-DQA1 and HLA-DQB1 loci have an application in the clinical practice of Celiac disease." (PMID 23050549, 2012). "Alleles of the HLA-DQA1 and HLA-DQB1 genes are necessary for celiac disease but are not sufficient for disease development." (PMID 22615847, 2012). "We also found that the frequency of the missense mutation p.S229N of HLA-DQB1 gene in ASD patients (15/72 = 20.83%) was significantly higher than that in healthy controls (4/107 = 3.73%); it is well known that HLA-DQB1 is a susceptibility gene for celiac disease." (PMID 35741860, 2022). "The goal of this analysis was to test the hypothesis that the known HLA-DQA1 and HLA-DQB1 celiac disease high-risk alleles were not the only celiac disease alleles within the xMHC." (PMID 22615847, 2012).
diabetes (15 papers, 2008 to 2025). "In conclusion, we observed that rs9274619:A linked to HLA-DQB1/DQA2 is associated with reduced TGs only among adults with diabetes." (PMID 36269708, 2022). "BHLHE41 also has a role in immune function and in addition toCAMK1D,AGER is implicated in diabetes along with the narcolepsy-related gene,HLA-DQB1." (PMID 34745571, 2020). "Multivariate logistic regression analyses revealed that diabetes duration and systolic blood pressure were independent risk factors for the occurrence of chronic kidney disease in these patients and that the HLA-DQB1*0501 allele had a protective effect for DN." (PMID 23671871, 2013). "Recently, the tenth article highlights the importance of HLA-DQB1 in diabetes and suggests its function in this disease." (PMID 36360783, 2022). "ML algorithms highlighted the use of the HLA-DQB1 gene as a biomarker for diabetes early detection and provided several prediction models with moderate accuracy." (PMID 36360783, 2022). "A number of prediction models with fair accuracy were provided by ML algorithms, which also highlighted the use of the HLA-DQB1 gene as a biomarker for diabetes early detection." (PMID 36360783, 2022). "Machine learning algorithms highlighted the use of the HLA-DQB1 gene as a biomarker for diabetes early detection." (PMID 36360783, 2022). "Moreover, one diabetes associated SNP (rs9272346 HLA-DQA1, PT1D<10−128) was found through the proxy search to overlap with a cis-mQTL-SNP (rs1063355 HLA-DQB1, R2 = 0.87) that showed association with mRNA expression in the human islets." (PMID 25375650, 2014). "We next tested whether the associations with the 12q13 SNPs were dependent on other covariates such as gender of the subjects, age of onset of diabetes or HLA-DQB1 genotypes using logistic regression." (PMID 20668683, 2010). "When we examined the T2DM group who did not develop nephropathy, despite many years of diabetes, we found decreased frequencies of the HLA-DQA1*0302 and HLA-DQB1*0501 alleles compared to the non-DN group." (PMID 23671871, 2013).
rheumatoid arthritis (15 papers, 2005 to 2025). A chronic, systemic autoimmune disorder characterized by inflammation in the synovial membranes and articular surfaces. "Specific HLA alleles include HLA-DR3 and HLA-DR4 (associated with type 1 diabetes—T1D), as well as HLA-DRB1 (associated with rheumatoid arthritis—RA and multiple sclerosis—MS), HLA-DQB1 (associated with MS), and HLA-B27 (associated with AS)." (PMID 40507438, 2025). "For instance, several HLA-DRB1 alleles have been associated with susceptibility to rheumatoid arthritis (RA) in different populations, HLA-DQA1 and HLA-DQB1 alleles have been strongly associated with type-1 diabetes and celiac disease, and specific HLA-DRB3*03:01 allele with Crohn’s disease." (PMID 39835139, 2024). "The objective of this study was to examine HLA-DRB1 and HLA-DQB1 genotypes in patients with severe extra-articular rheumatoid arthritis (ExRA) and to compare them with the genotypes of rheumatoid arthritis (RA) patients without extra-articular manifestations." (PMID 16277691, 2005).
narcolepsy (14 papers, 2008 to 2024). A sleep disorder characterized by a tendency for excessive sleepiness during the day which occurs even after adequate sleep in the nighttime. "We observed that the most common susceptibility genes in patients with narcolepsy in this study were HLA-DQB1*0602/*0301/HLA-DQA1*0102/*0505." (PMID 38725645, 2024). "There is one common gene between narcolepsy and IR:HLA-DQB1, which is the narcolepsy associated gene under study here." (PMID 34745571, 2020). "Previously we showed that approximately 40% of the patients with EHS carry the HLA-DQB1*06:02 allele but that 12% of the general Japanese population and 100% of the patients with narcolepsy with cataplexy carry this allele." (PMID 23646285, 2013). "A correlation analysis with known genes associated with these disorders(LRRK2, HLA-DQB1, and HCRT) was used to query microarray data corresponding to brain regions known to be involved in PD and narcolepsy." (PMID 34745571, 2020). "HLA-DQB1*06:02 was a major genetic factor for the onset of narcolepsy, and the T cell receptor alpha gene (TRA) and purinergic receptor P2Y, G-protein coupled, 11 gene (P2RY11) were also reported to be associated with narcolepsy." (PMID 32223758, 2020). "This may be further emphasised by the observation that all children who developed narcolepsy after the Pandemrix® vaccination had HLA genotypes containing HLA-DQB1*06:02." (PMID 28990147, 2018). "HLA-DQB1 genotypes distribution in Mexican Mestizo patients with narcolepsy and controls." (PMID 18706091, 2008). "HLA-DQB1 distribution in Mexican Mestizo patients with narcolepsy and in healthy controls." (PMID 18706091, 2008). "Additionally several reports from other groups also indicate that HLA-DQB1*06:02 is associated with the pathogenesis of narcolepsy with cataplexy; given these finding, we believe that the pathogenesis of EHS may partially differ from that of narcolepsy with cataplexy." (PMID 23646285, 2013). "Interestingly, rs10988217 showed a similar tendency in its association with both HLA-DQB1*06:02 negative EHS and narcolepsy with cataplexy in both Japanese and Caucasian populations." (PMID 23646285, 2013). "The distribution of serum IgG was significantly different among healthy controls negative for the HLA-DQB1*0602 allele (11.66±3.55 mg/ml), healthy controls positive for the HLA-DQB1*0602 allele (11.45±3.43), narcolepsy patients (9.67±3.38), and idiopathic hypersomnia patients (13.81±3.80)." (PMID 20221267, 2010).
systemic lupus erythematosus (12 papers, 2010 to 2025). An autoimmune multi-organ disease typically associated with vasculopathy and autoantibody production. "Similarly, drug-induced lupus was linked to genetic predisposition, as evidenced by the correlation of minocycline-induced lupus with HLA-DQB1 alleles with tyrosine at position 30 and the association of HLA-DR4 with SLE induced by hydralazine." (PMID 27754327, 2016). "The lupus-associated variant in this SNP tags the lupus-associated classical alleles DRB1*03:01 and DRB1*15:01, and is associated with increased expression of HLA-DRB1, HLA-DQA1, and HLA-DQB1 in monocyte-derived dendritic cells." (PMID 35902632, 2022). "On this line, the MHC class II molecules HLA-DQB1 and HLA-DRB1, along with the MCH class I HLA-C, have been recently associated with resistance to systemic autoimmune diseases, such as systemic sclerosis, systemic lupus erythematosus and rheumatoid arthritis." (PMID 31511551, 2019). "Interestingly, many of the IgAN loci are known to exhibit opposing effects on other autoimmune conditions; for example, the HLA-DQB1 and HORMAD2 risk alleles are respectively protective for systemic lupus erythematosus, and inflammatory bowel disease." (PMID 22737082, 2012).
cervical carcinoma (11 papers, 2013 to 2024). A carcinoma arising from either the exocervical squamous epithelium or the endocervical glandular epithelium. "Our study points to the importance of expression level of HLA-DQA1 and HLA-DQB1 for the susceptibility to develop cervical carcinoma." (PMID 27285765, 2016). "A recent meta-analysis found the class II alleles HLA-DQR*02, -*03, and -*06:03 to decrease and HLA-DQB1*05, -*03:01, and -*04:02 to increase risk of cervical cancer, while a genome-wide study concluded HLA-DRB1*06:02 and -*15:01 to be major risk alleles in cervical carcinogenesis." (PMID 35363864, 2022). "Our findings combined with preclinical and clinical results in other cancer types suggest that the HLA class II receptor HLA-DQB1 may cause PD-1-dependent tumours in cervical cancer." (PMID 33723390, 2021). "Two genes within the 10-gene signature (LIMCH1 and HLA-DQB1) were selected for further analyses as potential prognostic markers in a large population-based cervical cancer cohort by IHC performed in TMAs." (PMID 33723390, 2021). "Reduced risk of HPV18-associated cervical cancer was seen with HLA Class II alleles (HLA-DRB1*13 (OR = 0.51, P = 0.0058), HLA-DQB1*0603 (OR = 0.42, P = 0.021) and HLA-DQA1*0103 (OR = 0.50, P = 0.041))." (PMID 28806749, 2017). "Susceptibility to HPV infection or cervical cancer and precancerous lesion development was associated with the HLA class II: HLA-DRB1 alleles; HLA-DQB1 alleles; HLA-DPB1 alleles; and classes I and II haplotypes." (PMID 23936772, 2013). "Furthermore, HLA-DQB1high tumours associated with inflammatory reaction, activated immune responses and PD-L1high levels pointing to HLA-DQB1 expression as a marker of immune activation in cervical cancer." (PMID 33723390, 2021). "Considering these findings, we suggest HLA-DQB1 as a potential marker for immune activation that may indicate a response to immunotherapy in cervical cancer." (PMID 33723390, 2021). "The UK Biobank cervical cancer GWAS, which combined CIN3 and invasive cervical cancer, confirmed variants at HLA-DQA1 (rs9272050), MICA (rs6938453), and HLA-DQB1 (rs55986091), of which HLA-DQA1 (rs9272050) was also replicated at a genome-wide significance in the FinnGen biobank cohort." (PMID 34680286, 2021). "HLA-DQB1 is more extensively studied in gastric cancer and cervical cancer." (PMID 33585219, 2020). "Overall, three haplotypes, HLA-DRB1*15/HLA-DQB1*0602/HLA-DQA1*0102, HLA-B*0702/HLA-C*0702, and HLA-DRB1*0401/HLA-DQA1*0301, were associated with increased risk of both HPV16 and HPV18-associated cervical cancer, and for the development of both squamous cell carcinoma and adenocarcinoma." (PMID 28806749, 2017). "Considering HPV18-associated cervical cancer (n = 166 cases), association with increased risk was strongest with HLA-DRB1*15 (OR = 1.68, P = 0.0013) and HLA-DQB1*0602 (OR = 1.65, P = 0.0030), with only nominal HLA Class I risk associations seen with HLA-B*0702 and HLA-C*0702." (PMID 28806749, 2017). "Two of the signature genes, HLA-DQB1 and LIMCH1, displayed independent prognostic significance when investigated in a large population-based patient cohort by IHC, indicating a promising role as prognostic biomarkers guiding cervical cancer treatment." (PMID 33723390, 2021). "HLA-DQB1 and LIMCH1 are potential biomarkers guiding cervical cancer treatment." (PMID 33723390, 2021).
melanoma (10 papers, 2004 to 2025). A malignant, usually aggressive tumor composed of atypical, neoplastic melanocytes. "HLA-DQB1 * 0301 has been reported to be closely associated with the risk of melanoma development and progression." (PMID 33585219, 2020). "This conclusion is consistent with previous studies in which HLA-DRB1*04 was associated with melanoma, because HLA-DQB1*0301 is in linkage disequilibrium with HLA-DRB1*04." (PMID 15310399, 2004). "HLA-DQB1*03:01 was found overrepresented in Caucasian patients with melanoma and independently predicted recurrence and metastasis." (PMID 33687539, 2022). "The alleles that differed among melanoma patients were HLA-A*03, HLA-B*037, *53, *54, *58, *59, *78, HLA-DRB1*1102, HLA-DQB1*0201, and *0302 with corresponding P values .042.033.050.046.001.021.004.021.006 and .033, respectively." (PMID 20549830, 2010). "Furthermore, the frequency of HLA-DQB1*0301 and HLA-DQB1*0303 alleles are highly expressed in melanoma patients." (PMID 32310824, 2020). "Because the 4 genes IGHV1-18, CXCL11, LTF and HLA-DQB1 are associated with tumor immunity, we used the TIMER database to analyze the correlation between the prognosis of these 4 genes and the infiltration of immune cell subtypes in melanoma." (PMID 33585219, 2020). "Moreover, Veatch and colleagues recently identified HLA-DQB1*03-restricted BRAFV600E-specific CD4+ T cells in an acral melanoma patient, who nonetheless developed metastases under ipilimumab (anti-CTLA-4) immunotherapy." (PMID 31998317, 2019). "In this study, we focused on the immune infiltrating status in melanoma and selected IGHV1-18, CXCL11, LTF and HLA-DQB1 from immune cell infiltration cluster as immune cell infiltration-related DEGs through the analysis of differences in melanoma samples and the construction of prognostic models." (PMID 33585219, 2020). "Compared with the normal melanocytes, IGHV1-18, CXCL11 and HLA-DQB1 were highly expressed in melanoma cell line A375, A815 and SK-MEL-28, and LTF was downregulated in melanoma cell line A375, A815 and SK-MEL-28, and both had statistical significance (P < 0.05)." (PMID 33585219, 2020).
multiple sclerosis (10 papers, 2007 to 2025). A progressive autoimmune disorder affecting the central nervous system resulting in demyelination. "Multiple sclerosis (MS) is a complex trait in which alleles at or near the class II loci HLA-DRB1 and HLA-DQB1 contribute significantly to genetic risk." (PMID 18606010, 2008). "Three HLA alleles had evidence for association with depression after correcting for multiple testing (p < .004): HLA-B*08:01 and HLA-DQB1*02:01 (SLE) and HLA-DRB1*03:01 (multiple sclerosis, primary adrenocortical insufficiency, SLE)." (PMID 31570195, 2020).